PIK3CA (phosphatidylinositol-4,5-bisphosphate 3-kinase catalytic subunit alpha)
Diseases named in the same sentence as PIK3CA in open-access papers (continued):
Sharing a sentence is not in itself a finding about the gene and the disease.
primary hyperparathyroidism (1 paper, 2020). Hyperfunction of the parathyroid glands resulting in the overproduction of parathyroid hormone. "Further studies, particularly those demonstrating the ability of activating PIK3CA mutations to experimentally drive primary hyperparathyroidism, would be valuable for providing a model system in which the basis of malignant behavior in the parathyroid cell context can be investigated." (PMID 32537547, 2020).
pulmonary adenoid cystic carcinoma (1 paper, 2015). "The data presented in this work suggest that EGFR, KRAS, BRAF, ALK, PIK3CA, PDGFRA, and DDR2 may not be driver genes in primary pulmonary adenoid cystic carcinoma." (PMID 26373952, 2015).
relapsing (1 paper, 2024). "According to our multivariate analysis, PIK3CA status did not appear to be as crucial as lymph node involvement (HR = 2.76; p = 0.03) or tumor grade (HR = 2.18; p = 0.08) in relapsing disease." (PMID 39235099, 2024).
Rhabdoid Meningioma (1 paper, 2022). A WHO grade III meningioma characterized by the predominant presence of rhabdoid cells forming sheets. "In this regard, SMO, AKT, and PIK3CA mutations are typical of anterior skull base meningiomas, whereas KLF4 mutations are specific for secretory histology, and BAP1 alterations are common in progressive rhabdoid meningiomas." (PMID 35565385, 2022).
seborrheic keratosis (1 paper, 2021). A common benign skin neoplasm usually affecting older individuals. "By analogy, somatic mutations in oncogenic fibroblast growth factor receptor 3 (FGFR3) or phosphatidylinositol-4,5-bisphosphate 3-kinase catalytic subunit alpha (PIK3CA) result in seborrheic keratosis (senile wart) or epidermal nevi." (PMID 33800195, 2021).
Sepsis (1 paper, 2023). Sepsis is defined as life-threatening organ dysfunction caused by a dysregulated host response to infection. "The role of PIK3CA in sepsis was further studied by RNA sequence analysis of shPIK3CA-transfected plasma samples." (PMID 37285838, 2023). "It was found in GSE154918 that the expression of PIK3CA was down-regulated in sepsis compared with that in normal samples." (PMID 37285838, 2023). "It was found through Gene Expression Omnibus (GEO) database that the expression of phosphatidylinositol 3-kinase catalytic subunit alpha (PIK3CA) was down-regulated in sepsis compared with that in normal samples." (PMID 37285838, 2023). "The results showed that sepsis miR-506-3p OE group had significantly decreased expressions of PIK3CA, PI3K and mTOR (p < 0.01), and significantly increased expressions of Beclin, LC-3II and ATG5 compared with sepsis miR-506-3p OE NC group (p < 0.01)." (PMID 37285838, 2023).
SHORT syndrome (1 paper, 2021). A rare disorder characterized by multiple congenital anomalies, including short stature, hyperextensibility of joints, ocular depression, Rieger anomaly and teething delay in which the cause of the disease is a mutation in PIK3R1 gene. "Biochemical studies demonstrate that differences between SHORT syndrome and APDS2 are attributable to different profiles of activation or repression of PIK3CA and PIK3CD by mutant PIK3R1 products." (PMID 34040190, 2021).
squamous cell carcinoma in situ (1 paper, 2020). "No PIK3CA mutation was found in the only squamous cell carcinoma in situ (SIS) patient." (PMID 31692283, 2020).
squamous cell tumors (1 paper, 2015). "We did not observe enough recurrent cases (2 relapses in 12 cases with PIK3CA mutations) to effectively evaluate the association between PIK3CA mutation status and RFS in the subgroups of patients with non-squamous cell tumors." (PMID 26358014, 2015).
supraglottic cancers (1 paper, 2020). "Of note, cancer related proteins RB1, CHEK2, CCNE1, S6 and PIK3CA were higher in the supraglottic cancers, whereas PDL1 was higher in the glottic cancers." (PMID 33396315, 2020).
Ta (1 paper, 2024). "In Ta tumors, the most frequent gene variants were FGFR3 (48%) and PIK3CA (26%), and the most common amplifications were AKT1 (24%), FGFR3 (13%), MYCN (11%), and CCND1 (11%)." (PMID 39410541, 2024). "Our analysis identified two subgroups in Ta tumors: one with FGFR3 alterations linked to LG tumors and favorable outcomes, and another with alterations in ERBB2, PIK3CA, and ERBB3 mutations, and FGFR1, CCND1, and MYC amplifications, associated mostly with HG tumors and poorer prognosis." (PMID 39410541, 2024).
tauopathy (1 paper, 2021). Neurodegenerative disorders involving deposition of abnormal tau protein isoforms (tau proteins) in neurons and glial cells in the brain. "Problem 2 asked participants to predict compounds that bind the Tauopathy pro-targets AURKA, PAK1, FGFR1, and STK11 and avoid the Tauopathy anti-targets PAK3, MAP3K7, and PIK3CA." (PMID 34520464, 2021). "Problem 2 asked participants to predict compounds that bound the Tauopathy pro-targets, AURKA, PAK1, FGFR1, and STK11 and did not bind PAK3, MAP3K7, and PIK3CA." (PMID 34520464, 2021).
testicular tumors (1 paper, 2021). "KRAS mutations were present in 10% of testicular tumors, while fewer than 5% of samples contained mutations in NRAS, PIK3CD, and PIK3CA genes." (PMID 34819066, 2021).
thoracic cancer (1 paper, 2019). A primary or metastatic malignant neoplasm affecting the tissues of the thorax. "PIK3CA is also frequently altered in thoracic cancer, particularly in SCC (71%), indicating that it may have significance as a therapeutic target." (PMID 31632972, 2019).
thoracic tumors (1 paper, 2025).
tonsil (1 paper, 2023). "PIK3CA and RTK pathway gene mutations, on the other hand, were not correlated with OS or DFS in the TCGA tonsil cancer cohort, even in the HPV-positive group." (PMID 36979829, 2023).
tonsil cancer (1 paper, 2023). A primary or metastatic malignant neoplasm that affects the tonsil. "TCGA tonsil cancer showed the same mutation rate in the HPV-positive group (7/8, 87.5%) and only one PIK3CA mutation (E545K) was noted in the HPV-negative group." (PMID 36979829, 2023).
tracheal squamous cell carcinoma (1 paper, 2016). "A parotid carcinosarcoma patient and tracheal squamous cell carcinoma patient who both had PIK3CA mutation (H1047R) showed PR and SD (−21%) to everolimus, respectively." (PMID 27105424, 2016).
urinary system disease (1 paper, 2021). "Moreover, the results of Open Targets also suggest that PIK3CA was associated with immune system disease and urinary system disease." (PMID 34367282, 2021).
urothelial carcinoma of the renal pelvis (1 paper, 2020). "Indeed, PIK3CA mutations are considered as an early genetic alteration associated with FGFR3 mutations in superficial papillary NMIBC and the activation of the PI3K/AKT pathway is identified to induce urothelial carcinoma of the renal pelvis." (PMID 32333246, 2020).
vaginal cancer (1 paper, 2025). A primary or metastatic malignant neoplasm involving the vagina. "PIK3CA: PIK3CA has not been greatly studied within vaginal cancer." (PMID 40647429, 2025).
viral pneumonia (1 paper, 2026). Inflammation of the lung parenchyma that is caused by a viral infection. "Through the construction of a comprehensive PPI network, we identified six core targets, including STAT3, AKT1, PIK3CA, PIK3R1, JUN, and MAPK1, which are likely central to the mechanism of action of DLQGD in viral pneumonia." (PMID 41601832, 2026).
yolk sac tumor (1 paper, 2020). A non-seminomatous malignant germ cell tumor composed of primitive germ cells. "An analysis of 87 MOGCTs identified recurrent mutations in KIT and KRAS, along with frequent focal amplifications of PIK3CA and AKT1 in yolk sac tumors." (PMID 32455595, 2020).
tumor (2,564 papers, 2005 to 2026). "Clinically, PIK3CA mutations and pathway activation have been linked to higher tumor mutation burden and poorer prognosis, including worse progression-free and overall survival." (PMID 41597409, 2026). "In this hyperactivation, PTEN, a tumour suppressor, commonly has loss-of-function mutations, and PIK3CA, encoding the catalytic subunit of PI3K, has gain-of-function mutations, leading to unchecked endpoints of PIP3 and then AKT activation." (PMID 41476776, 2026). "Targeted therapies for PDGFRA and PIK3CA mutations can control tumor growth and metastasis but face challenges like drug resistance and high costs." (PMID 41799769, 2026). "Targeted therapies for PDGFRA and PIK3CA mutations control tumor growth but face drug resistance and cost issues." (PMID 41799769, 2026). "Administration of Everolimus also showed anti-tumor activity in two phase II studies including iCCA patients and in a case report of PIK3CA E545G mutated iCCA patient." (PMID 40260297, 2025). "According to tumor sequencing studies, somatic mutations in PIK3CA lead to tumor progression by enhancing PIK3CA function." (PMID 40050490, 2025). "Inspection of variants in genes linked to anti‐EGFR therapy (KRAS, BRAF, NRAS, PTEN and PIK3CA) revealed variability across tumours and fractions." (PMID 40302146, 2025). "In the PALOMA-3 study, circulating tumor DNA (ctDNA) sequencing identified the emergence of PIK3CA driver mutations during treatment." (PMID 39935426, 2025). "Other co-existing genetic alterations associated with tumor progression and shorter survival in oligodendroglioma include homozygous PIK3CA mutation, TCF12 mutation and increased MYC signaling." (PMID 40949165, 2025). "Its development is driven by multifactorial processes, including genetic mutations (e.g., in *BRCA1/BRCA2* and PIK3CA genes) and hormonal influences such as prolonged estrogen exposure, which promote tumor initiation and progression." (PMID 40510030, 2025). "Concurrently, copy number alterations resulting from PIK3CA gene amplification are strongly linked to hyperactivation of the PI3K pathway in tumor tissues." (PMID 40861811, 2025). "PIK3CA mutations can lead to altered signaling pathways that affect tumor microenvironment characteristics, such as immune cell infiltration." (PMID 41249701, 2025). "Each of the 13 tumours harboured at least one somatic mutation, with PIK3CA the most frequently mutated gene, (5 mutations in 5/13 tumours; 38%)." (PMID 41364261, 2025). "Constitutive PI3K/Akt signaling (often from PTEN tumor suppressor loss or PIK3CA mutations common in HNSCC) enables cancer cells to proliferate and survive under immune attack, and also alters the TME." (PMID 41374963, 2025). "Biomarkers such as PD-L1 CPS ≥ 1%, ARID1A mutations, elevated tumor mutational burden, and PIK3CA alterations emerge as promising predictors of therapeutic response." (PMID 41020848, 2025). "Regarding the cell migration point, both the KRAS and PIK3CA mutations promote cell migration, leading to aggressive tumor growth and metastasis." (PMID 40806644, 2025). "p110α, the catalytic subunit of the PI3Kα complex required for normal growth and proliferation, is required for tumor signaling and growth caused by PIK3CA mutations or RTKs." (PMID 40050490, 2025). "Mutations in PIK3CA, particularly hotspot variants in exons 9 (helical domain, e.g., E545K) and 20 (kinase domain, e.g., H1047R), are present in up to 40% of ER+/PR+ tumours." (PMID 41425867, 2025).
tumor (continued). "PIK3CA alterations were associated with a number of favorable prognostic features: smaller tumor size, lower grade, Ki67 <20%, and positive PR status (p ≤ 0.005 for all comparisons)." (PMID 40507317, 2025). "In their study of 68 patients with advanced cancers, the authors reported an 85% detection rate of PIK3CA mutations in tumor tissue and 74% in circulating tumor DNA (ctDNA)." (PMID 40050490, 2025). "Mutations in the PIK3CA gene represent a common mechanism of activation in this pathway, closely linked to tumor cell proliferation, survival, invasion, and metastasis." (PMID 40328748, 2025). "Alterations in the PI3K/AKT/mTOR signaling pathway result in a disruption of regulatory cellular processes; therefore, PIK3CA mutations increase tumor cells proliferation, migration and invasion, as well as resistance to apoptosis." (PMID 40227634, 2025). "Prior research has indicated that PIK3CA mutation is a crucial factor in the malignant transformation of tumor cells and therapy resistance." (PMID 40328748, 2025). "PIK3CA mutations impact the tumor immune microenvironment through various mechanisms, including facilitating the infiltration of immune-suppressive cells and impairing the function of effector T cells." (PMID 40328748, 2025). "Previous GEMMs with Pik3ca mutations often exhibit long tumor latency times, sometimes taking more than a year for tumor growth." (PMID 39808497, 2025). "For example, further study is needed to understand the exact role of PIK3CA mutations in promoting tumor cell proliferation and drug resistance." (PMID 41404730, 2025). "Accumulating evidence suggests that the impact of PIK3CA mutations on tumor behavior and prognosis depends on the BC subtype." (PMID 40507317, 2025). "Parallel observations in the circRNA combination cohort revealed sustained downregulation of key classical oncogenes (PIK3CA) and novel tumor-associated genes (ANXA2, KIF2A, NCAPG2, PAIP1)." (PMID 40426998, 2025). "Inhibiting PI3Kα signalling with the PI3Kα inhibitor (PI3Kαi) alpelisib in combination with the ER degrader fulvestrant improved progression-free survival in patients with confirmed tumour-tissue PIK3CA mutations." (PMID 40263319, 2025). "After 21 days, PIK3CA mutation accelerated tumor growth, and cobomarsen treatment resulted in a significant reduction in the average volume of PIK3CAMUT tumors." (PMID 41281644, 2025). "The identification of a particular mutation in PIK3CA, known as PIK3CA H1047R, was found to augment tumor growth when treated with immunotherapy through a decrease in CD8+ T cells and a rise in inhibitory myeloid cells." (PMID 40740483, 2025). "PIK3CA mutations were significantly associated with tumor quadrant distribution, histological subtype, advanced clinical stage, perineural invasion, and high NLR, but no significant impact on DFS was observed." (PMID 40472482, 2025). "At least 3% of pancreatic cancer patients carry PIK3CA gene mutations, which result in tumorigenesis and contribute to tumor proliferation." (PMID 39972450, 2025). "PIK3CA mutations exist in approximately 26% of BC overall, and are associated with favourable characteristics, such as lower tumour grade and decreased rates of lymph node metastases." (PMID 39470669, 2025). "PTEN p.Asp162Glu, p.Phe21fs, and PTEN 1027‐1G > T mutations were found in three right‐sided and one left‐sided tumour, and PIK3CA p.Gln546Lys and p.Gln546Glu mutations in two left‐sided tumours." (PMID 40302146, 2025). "In parallel, aberrations in the PI3K/AKT/mTOR signaling pathway, particularly activating PIK3CA mutations, contribute to endocrine resistance and tumor proliferation." (PMID 41514640, 2025).